CDX2 (caudal type homeobox 2)
Diseases named in the same sentence as CDX2 in open-access papers (continued):
Sharing a sentence is not in itself a finding about the gene and the disease.
gastric cancer (continued). "However, SOX2 suppression may be permissive for a sub-set of gastric cancers with CDX2 induction to acquire mutations in epigenetic modifier genes, including ARID1A, KMT2D, KMT2C, KMT2A, and KMT2B." (PMID 40149431, 2025). "Given the association of CDX2 induction with the suppression of HLA II molecules, therapeutic approaches that prevent or reverse intestinal metaplasia and CDX2 induction may enhance the immunogenicity of gastric cancers." (PMID 40149431, 2025). "Moreover, increased CDX2 expression was associated with a more metastatic phenotype of gastric carcinoma cells, whereas CDX2 might act as a tumor suppressor during colorectal carcinogenesis." (PMID 35331316, 2022). "Inversely, CDX2 is ectopically turned on outside the gut in precancerous intestine-type metaplasia and associated adenocarcinoma of foregut-derived organs including stomach and esophagus, even though patients survival correlates with the CDX2 level in gastric cancers." (PMID 34759958, 2021). "As a group, gastric cancers with mRNA CDX2 induction display differences both in the genomic alterations and in the immune presentation machinery compared with gastric cancers with no CDX2 mRNA induction." (PMID 40149431, 2025). "It is noteworthy that GATA6 and CDX2 were both enriched in our DGC analysis—this combination likely reflects the intestinal-type gastric cancers that commonly arise in the distal stomach." (PMID 40862793, 2025). "The role of stem cell transcription factors SOX2 and CDX2 is of particular interest in the pathogenesis of gastric cancer." (PMID 40149431, 2025). "The source series has examined several clinical characteristics in a substantial number of patients with gastric cancer but only a sub-set had CDX2 over-expression, reducing the eligible patients in this study." (PMID 40149431, 2025). "Consistent with our results, CDX2-positive gastric cancers have been reported to be less aggressive, showing better differentiation, lower invasive stage, and markedly improved survival compared to CDX2-negative cancers." (PMID 40862793, 2025). "TRPS1 and GATA3 immunohistochemical stains should be considered for differentiating primary from secondary breast cancer, while CDX2 is in favor of primary gastric cancer." (PMID 40936680, 2025). "In turn, ELF4 transactivates the expression of caudal type homeobox 2 (CDX2), thereby boosting growth, migration, invasion, and metastasis of gastric cancer." (PMID 40083328, 2025). "Fucoidan significantly increased the expression of CLEC-2 in gastric cancer cells by modulating CDX2, a critical regulator of gut homeostasis, thereby inhibiting gastric cancer progression." (PMID 39517244, 2024). "The group of gastric cancer patients with induced CDX2, defined as mRNA expression z-score relative to all samples above 0, consisted of 240 patients (54.5% of the patients of the entire cohort) in the TCGA cohort." (PMID 39768557, 2024). "With these considerations in mind, therapies inhibiting the molecular network inducing the metaplastic changes, in which CDX2 plays a key role, would constitute a fundamental advancement in gastric cancer therapeutics." (PMID 39768557, 2024). "A significant percentage of gastric cancers, albeit varying according to the criteria of positivity used and the population studied, express CDX2." (PMID 39768557, 2024). "The expression of two other transcription factors, ELF3 and KLF5, also correlated with the expression of CDX2 in gastric cancer (Spearman correlation coefficient 0.21, p = 1.07 × 10−5, and Spearman correlation coefficient 5.49, p = 1.07 × 10−13, respectively)." (PMID 39768557, 2024). "In gastric cancer cells, Oct1 is recruited to the CDX2 promoter but loses its ability to activate transcription, highlighting its complex regulatory role." (PMID 39026223, 2024). "CDX2 protein positivity was associated with better prognosis in EBV-negative, MMR-proficient gastric cancers in a series of 1158 advanced gastric cancer patients." (PMID 39768557, 2024).
gastric cancer (continued). "In this investigation, the clinical and genomic profile of gastric cancers with CDX2 up-regulation is compared with the profile of gastric cancers with suppressed CDX2 expression." (PMID 39768557, 2024). "A master regulator of the endoderm intestinal differentiation, HNF4α showed a strong co-expression with CDX2 at the mRNA level in the TCGA gastric cancer cohort." (PMID 39768557, 2024). "In a series of 80 gastric cancer patients from the Middle East, 38.7% of gastric cancers expressed CDX2, defined as at least 10% of cancer cells with nuclear staining in immunohistochemistry sections." (PMID 39768557, 2024). "PD-L1 mRNA expression was lower in gastric cancers with increased CDX2 expression compared with gastric cancers with low CDX2 expression (Student’s t test p < 0.0001)." (PMID 39768557, 2024). "Other established target genes of CDX2, such as MUC2, are upregulated by CDX2 in gastric cancers, as confirmed previously and herein." (PMID 39768557, 2024). "For example, Tumor-derived exosomes carrying LINC01091 facilitated gastric cancer (GC) progression through mediating miRNA-128-3p/ELF4/CDX2 axis." (PMID 39425009, 2024). "Diffuse histology and high grade were less prevalent in gastric cancers with higher CDX2 expression (χ2 test p = 0.02 and Fisher’s exact test p = 0.0004, respectively)." (PMID 39768557, 2024). "Among other gastric cancer-associated genes, the epigenetic modifier KMT2B was also more frequently mutated in cancers with higher CDX2 expression (12.6% versus 3.2% in cancers with lower CDX2, Fisher’s exact test p = 0.03)." (PMID 39768557, 2024). "Another inflammation-related signaling cascade inducing CDX2 in gastric cancer cells is the interleukin 6 (IL6) cascade, which activates JAK/STAT and ERK/MEK signaling." (PMID 39768557, 2024). "CDX2 up-regulated the expression of receptor tyrosine kinase EphB2 and reduced the migration of gastric cancer cells." (PMID 39768557, 2024). "Gastric cancer patients with higher CDX2 expression were older (mean age 66.5 years old) than patients with suppressed CDX2 expression (mean age 61.9 years old, Student’s t test p < 0.001)." (PMID 39768557, 2024). "In a series of 92 localized gastric cancer patients from Spain, who underwent surgical resection, 68.5% of tumors were CDX2 positive." (PMID 39768557, 2024). "Ectopic cdx2 expression in the stomach induced gastric intestinal metaplasia in transgenic mice, and CDX2 is induced in intestinal gastric metaplasia and gastric carcinomas." (PMID 39768557, 2024). "LINC01091 can coordinate the microRNA-128-3p/ELF4/CDX2 axis and thus promote gastric cancer growth and metastasis by way of exosomes on one hand and can act as hub lncRNA in DNA methylation-related prognostic signatures of prostate cancer." (PMID 37822927, 2023). "Xanthurenic acid (XA) was measured in gastric cancer cells treated with H. pylori or H. pylori virulence factor, respectively, and qPCR and WB were performed to detect CDX2 and key metabolic enzymes expression." (PMID 37328804, 2023). "Caudal‐Type homeobox 2 (Cdx2), a member of the caudal‐related homeobox transcription factor gene family, has also been reported to facilitate claudin‐4 expression in gastric carcinoma cells." (PMID 36799102, 2023). "Meanwhile, REG4 expression was significantly associated with both the intestinal mucin phenotype (mucin 2 [MUC2] and CDX2) and neuroendocrine differentiation of gastric cancer." (PMID 36172286, 2022). "It was confirmed by immunohistochemistry that the expression level of CDX2 was elevated in patients with early gastric cancer." (PMID 35847930, 2022).
gastric cancer (continued). "For instance, CDX2 down‐regulated by miR‐9 participates in biological progression of gastric cancer." (PMID 33621425, 2021). "For instance, miR-9 is responsible for gastric malignancies by targeting CDX2, conferring among others to enhanced proliferation of gastric cancer cells and MUC2 expression." (PMID 34183045, 2021). "Our study further demonstrated that CDX2 expression was positively correlated with Reg IV expression in gastric cancer tissues." (PMID 33639844, 2021). "Our study demonstrated that CDX2 expression was positively correlated with that of Reg IV in gastric cancer." (PMID 33639844, 2021). "Previous evidence shows CDX2 inhibits gastric cancer cell invasion and metastasis by upregulating cell junction protein E-cadherin and Claudin-2." (PMID 33621200, 2021). "Reports have shown that CDX2 expression is negatively correlated with lymph node metastasis, tumor invasion, and survival in gastric cancer." (PMID 33639844, 2021). "Low CDX2 expression was frequently observed in gastric cancer tissues with low Reg IV expression (72.6%, 45 of 62 cases), and high CDX2 expression was frequently observed in tissues with high Reg IV expression (67.7%, 21 of 31 cases; p = 0.0002 by χ2-test)." (PMID 33639844, 2021). "In the present study, Reg IV expression was also positively regulated by CDX2 in gastric cancer cells." (PMID 33639844, 2021). "Alternatively, CDX2 silencing significantly inhibited the growth of MGC-803 human gastric cancer cells and reversed the progression of MDR in SGC-7901/DDP cells in vitro and in vivo." (PMID 33639844, 2021). "In gastric cancer, CDX2 inhibits cell invasion and metastasis by upregulating the adhesion protein E-cadherin and inhibiting EMT." (PMID 33621200, 2021). "Results from this study demonstrated the following: First, there was a significantly positive correlation between the expression of CDX2 and Reg IV at the mRNA and protein levels in gastric cancer tissues." (PMID 33639844, 2021). "CDX2 and Reg IV were examined in gastric cancer specimens and paired adjacent tissues via real-time PCR and immunohistochemistry (IHC)." (PMID 33639844, 2021). "In this study, we investigated the correlation between CDX2 and Reg IV in gastric cancer tissues and cell lines, and the effect of CDX2 on migration and invasion in gastric cancer cells in vitro." (PMID 33639844, 2021). "A positive correlation was observed between CDX2 and Reg IV expression at the mRNA and protein levels in gastric cancer tissues." (PMID 33639844, 2021). "Our findings demonstrate that CDX2 expression was positively correlated with that of Reg IV in gastric cancer, and CDX2 promoted cell migration and invasion through upregulation of Reg IV expression in AGS and MKN-45 cells." (PMID 33639844, 2021). "Immunohistochemical staining of CA199, CK-7, and CDX-2 was positive, further confirming that heteromorphic cells were human gastric cancer cells." (PMID 32337226, 2020). "For instance, miR-9-5p suppresses prostate cancer progress by targeting StarD13, and miR-9 downregulates CDX2 expression in gastric cancer cells." (PMID 32121275, 2020). "CDX2 is expressed in all gastric carcinomas that develop an intestinal phenotype, but it is also present in a proportion of cases with gastric phenotype." (PMID 33023082, 2020). "Previous studies have reported that CDX2 transgenic mice can develop IM and gastric cancer, highlighting CDX2 as a molecular trigger in IM and carcinogenesis." (PMID 30733645, 2019). "In these differentiated/CDX2-positive gastric cancer cases, CLDN4 is at high levels than undifferentiated/CDX2-negative cases." (PMID 31040910, 2019). "In the pathway of gastric carcinoma development, especially the intestinal type, the mucosal changes from AG to IM are influenced by many variables, including low acidity, CDX2 expression, D1S191 instability, and telomere reduction." (PMID 31071187, 2019).
gastric cancer (continued). "CDX2 expression level is the lowest in the advanced gastric cancers, and it is also very decreased in the early onset of gastric cancers, indicating the possibility to act as a tumor suppressor." (PMID 29867026, 2018). "Individual studies have partially revealed the favourable prognostic roles of CDX2 expression in gastric cancers." (PMID 29179508, 2017). "For instance, the transcription factor Cdx2 can enhance the expression of claudin-3 and -4 in gastric cancer cells, and the transcription factor RUNX3 can enhance the expression of claudin-1 by binding to its promoter region." (PMID 28350854, 2017). "A study on CDX2 heterozygous knockout mice demonstrated CDX2 haploinsufficiency led to an increase in mTOR kinase activity and CDX2 overexpression in gastric cancer cells induced an increase of mTOR mRNA and protein expression." (PMID 29156556, 2017). "Data from miRNA target prediction databases and a literature search identified numerous tumor suppressive targets of the oncogenic miR-9, including FOXO1 in both non-small cell lung cancer and endometrial cancer and CDX2 in gastric cancer." (PMID 27612152, 2016). "This subgroup, showing SOX2 expression but a down-regulated expression of CDX2, has previously been shown to predict a worse patient outcome in gastric cancer." (PMID 27411517, 2016). "CDX2 had an inhibitory effect on the MGC-803 human gastric cancer cell line and promoted tumor cell apoptosis in vivo." (PMID 25738600, 2015). "The aim of the present study was to examine the effects of CDX2 on the growth of the MGC-803 human gastric cancer cell line in vivo, and to elucidate the mechanism involved." (PMID 25738600, 2015). "In CDX2, the ground truth image metastasis of gastric cancer is colored brown, and the hepatocytes and inflammatory cells are colored blue." (PMID 26099963, 2015). "This suggests that the overexpression of CDX2 induced apoptosis by altering the Bax/Bcl-2 ratio to suppress gastric cancer growth." (PMID 25738600, 2015). "In our previous study, the overexpression of CDX2 exhibited a significant effect on cell growth and proliferation in an in vitro cell model of gastric cancer." (PMID 25738600, 2015). "Our aim was to analyze the clinical relevance of SOX2 and CDX2 expression in gastric cancer biology." (PMID 25300947, 2014). "We showed, for the first time, that SOX2 combined with CDX2 expression profile in gastric cancer segregate patients into different prognostic groups, complementing the clinicopathological information." (PMID 25300947, 2014). "As tumors that are more differentiated generally behave in a less aggressive fashion, we questioned the relevance of two differentiation markers, SOX2 and CDX2, for the biological behavior of gastric cancers." (PMID 25300947, 2014). "In conclusion, we show for the first time that SOX2 together with CDX2 expression profiles in gastric cancer contributes to segregate patients into different prognostic groups, complementing the clinicopathological information." (PMID 25300947, 2014). "Here, we used a retrospective, observational study to assess the expression and prognostic value of the transcription factors SOX2 and CDX2 in gastric cancer." (PMID 25300947, 2014). "It has also been shown that caudal type homeobox 2 (Cdx2) is important in the regulation of intestinal claudin expression, not only in gastric mucosa with intestinal metaplasia, but also in gastric carcinoma." (PMID 24765156, 2014). "CDX2 expression was assessed in gastric carcinoma cell lines and nanoparticles behaviour in gastrointestinal mucus was tested in mouse explants." (PMID 24925340, 2014). "It is also indicated that miR-9 can modulate the proliferation of gastric cancer cells via targeting the caudal type homeobox 2 (CDX2) and NF-kappa B (NF-κB)." (PMID 23383271, 2013).
gastric cancer (continued). "A study of Cdx2-transgenic mice demonstrated that IM plays a significant role in the genesis of gastric carcinoma and that the cancer cells originated from intestinal metaplastic epithelial cells that had been entirely transformed from gastric cells by Cdx2." (PMID 24340024, 2013). "Increased cdx-2 expression was used as a marker for progression in gastric carcinogenesis, while some of the gastric cancers studies showed aberrant expression of cdx-2 in intestinal metaplasia which is a subset of gastric adenocarcinoma." (PMID 22824143, 2012). "A number of reports suggest that Cdx2 expression is a characteristic feature of human gastric cancer and served as a potential biomarker of tumor progression in early gastric carcinoma." (PMID 23181722, 2012). "Several investigators reported that Cdx2 reduced cell proliferation rates, and Cdx2-positive expression was decreased progressively with the depth of tumor invasion and advancing stage of gastric cancer." (PMID 23181722, 2012). "In summary, Cdx2 is a prognostic factor in gastric cancer, which acts as a marker of good outcome in patients with gastric cancer." (PMID 23181722, 2012). "So far several studies have demonstrated that Cdx2-positive expression in gastric cancer was significantly correlated with better differentiation and lower rate of lymph node metastasis." (PMID 23181722, 2012). "Cdx2-posititive gastric cancer patients also displayed higher 5-year survival rate than Cdx2-negative." (PMID 23181722, 2012). "In gastric carcinomas CDX2 expression was more common in intestinal type tumors than in diffuse type carcinomas (77% versus 45%, χ2 = 6.284; p = 0.012)." (PMID 22268990, 2012). "In gastric carcinomas, CDX2 expression was more common in intestinal type tumors than in diffuse type carcinomas." (PMID 22268990, 2012). "Conversely, among gastric carcinomas CDX2 positivity was more common in low grade carcinomas than in high grade carcinomas (80% versus 51%, χ2 = 4.584; p = 0.032)." (PMID 22268990, 2012). "In 55% of gastric carcinomas, CDX2 expression was found by immunohistochemistry, with higher levels of CDX2 expressions noted in carcinomas with intestinal-type morphology." (PMID 22074191, 2011). "Staining was used to detect Cdx1, Cdx2, Muc2 and Muc5AC and it was revealed that Cdx1 and Cdx2 were consistently expressed in IM and in a subset of gastric carcinomas." (PMID 19412438, 2007). "Immunohistochemical staining confirmed high CDX2 expression, a known prognostic factor in gastric cancer, in both primary gastric cancer tissues and organoids, consistent with its established role in intestinal metaplasia and gastric adenocarcinoma progression." (PMID 41154585, 2025). "Low expression of HLA II molecules in CDX2-induced gastric cancers may contribute to a cold immune environment and may also be a contributing factor in the immune tolerance of h." (PMID 40149431, 2025). "On the other hand, gastric cancers with CDX2 induction and SOX2-retained expression could benefit from future approaches targeting chromosome instability as a process." (PMID 40149431, 2025). "However, the two subgroups of CDX2-induced gastric cancers, with SOX2-maintained mRNA expression and SOX2 mRNA suppression showed minimal differences in member proteins of the immune presentation machinery." (PMID 40149431, 2025). "In conclusion, gastric cancers with CDX2 induction form two distinct groups according to SOX2 expression that could be used for guiding personalized targeted therapies." (PMID 40149431, 2025). "CDX2 has an important role in the specification of the lower gastrointestinal tract and, although it is not normally expressed in the stomach, it is induced in intestinal metaplasia and remains expressed in a sub-set of gastric carcinomas." (PMID 40149431, 2025).